HP (haptoglobin)
Diseases named in the same sentence as HP in open-access papers (continued):
Sharing a sentence is not in itself a finding about the gene and the disease.
gastritis (8 papers, 2017 to 2025). Inflammation of the stomach. "Given that HP urease test was positive and EBV DNA was detected in both her serum and gastric mucosa biopsy samples, a diagnosis of Hp gastritis or EBV-associated gastritis needed to be considered." (PMID 41142620, 2025).
Gilbert syndrome (8 papers, 2008 to 2023). An autosomal recessive inherited disorder characterized by unconjugated hyperbilirubinemia, resulting in harmless intermittent jaundice. "Majority of high-risk profiles (24/33) were abnormally low haptoglobin (hemolysis or anhaptoglobinemia), 4 subjects had abnormally high apoA1 value, 1 abnormally low ApoA1, 2 abnormally high GGT, one Gilbert syndrome with 72 micromol of unconjugated bilirubin, and one abnormally high A2 M." (PMID 20412588, 2010). "Among the 38 (0.51%) tests with RFPN, 31 (0.41%) were related to low haptoglobin, five to high ApoA1, two to high GGT, one to low ApoA1 and one to high bilirubin with proven Gilbert's syndrome." (PMID 21492460, 2011). "In patients with Gilbert syndrome, or any acute inflammation with high haptoglobin values, higher false-positive and false-negative rates were found." (PMID 18638013, 2008).
heart failure (8 papers, 2012 to 2025). Inability of the heart to pump blood at an adequate rate to meet tissue metabolic requirements. "Although her heart failure responded promptly to medical therapy, her renal function progressively deteriorated, ultimately requiring haptoglobin supplementation." (PMID 40606015, 2025). "The level of haptoglobin in plasma below 1.4 g/L predicted the occurrence of heart failure (according to NYHA 2, 3, 4) for one year with 100% sensitivity." (PMID 34948066, 2021). "Recently, Devaux's group identified haptoglobin as a potential biomarker of prognosis of heart failure in patients with acute MI." (PMID 22778955, 2012). "Another gene identified as heart - failure - specific one was haptoglobin (HP)." (PMID 24952741, 2014). "We identified haptoglobin as a potentially increased post-MI marker; nevertheless, studies with longer time points post-MI will have to be developed to confirm the role of haptoglobin in progression to heart failure." (PMID 22778955, 2012). "Interestingly, they state that low levels of haptoglobin early post-MI favor heart failure." (PMID 22778955, 2012).
anhaptoglobinemia (7 papers, 2008 to 2024). "In this review, we will outline the background of identification of complete haptoglobin gene deletion (HPdel), its geographical distribution, and several methods to diagnose congenital Hp deficiency (congenital anhaptoglobinemia) due to HPdel." (PMID 38672145, 2024). "Furthermore, these techniques are not designed to detect patients harboring the Hpdel allele that is, they cannot discriminate true anhaptoglobinemia from conditions of acquired undetectable haptoglobin levels." (PMID 23555085, 2013). "The father and another child (child 2) had low serum haptoglobin levels of 0.12 and 0.006 mg/mL, respectively, indicating hypohaptoglobinemia." (PMID 38672145, 2024). "In addition, we performed haptoglobin phenotyping, and showed, for the first time, that patient serum devoid of haptoglobin (anhaptoglobinemia) positively correlated with heroin dependence." (PMID 24743330, 2014). "However, true anhaptoglobinemia cannot be determined on the basis of the haptoglobin level alone because many acquired conditions might lower the haptoglobin concentrations to undetectable levels." (PMID 23555085, 2013). "The possible effect of genetics on haptoglobin levels is particularly important here, because one of the earliest studies on haptoglobin population genetics found that more than 30% of a Yoruba population in Nigeria lacked haptoglobin expression, a condition called anhaptoglobinemia." (PMID 37091678, 2023).
glioblastoma (7 papers, 2013 to 2024). The most malignant astrocytic tumor (WHO grade IV). "Being a cleaved and reassembled form of zonulin, haptoglobin also corresponds to therapeutic advances in glioblastoma patients with significantly decreased serum levels after adjuvant therapy." (PMID 39200114, 2024). "The study comprised 34 newly diagnosed glioblastoma patients, with blood samples collected before treatment for zonulin and haptoglobin analysis." (PMID 38254845, 2024). "Understanding the mechanisms involved in haptoglobin assembly could help identify molecular targets for reducing zonulin levels and improving glioblastoma patient prognosis." (PMID 38254845, 2024). "Pre-haptoglobin, which actually corresponds to zonulin, was already proposed as a possible glioblastoma biomarker because it is detected only in glioblastoma plasma but not in the plasma of healthy controls or other oncologic patients (e.g., patients with colon cancer)." (PMID 39200114, 2024). "Moreover, the expression of haptoglobin α2 was significantly elevated in glioma patients and positively correlated with tumor grade, being the highest levels detected in patients with glioblastoma; this postulates haptoglobin as a candidate biomarker for glioblastoma diagnosis and prognosis." (PMID 31284524, 2019). "In contrast, elastin microfibril interfacer 2 (Emilin2), guanine deaminase (GDA), haptoglobin (Hp) and selectin L (Sell) were enriched in macrophages/monocytes in RCAS and GL261 mouse models of glioblastoma." (PMID 38712663, 2024). "While acute phase proteins are expected to be elevated in stressful metabolic situations, haptoglobin reaches its highest levels in glioblastoma compared to acute phase reactions (not related to cancer) or other cancer." (PMID 39200114, 2024). "The determination of zonulin and haptoglobin levels was performed on serum samples from glioblastoma patients before surgery and without prior exposure to steroid treatment." (PMID 38254845, 2024).
Hepatitis (7 papers, 2014 to 2025). Inflammation of the liver. "For example, haptoglobin (Hp) responses to inflammation in cattle have been evaluated in acute bronchopneumonia, acute rumen acidosis, coliform mastitis, hepatic lipidosis, and transport stress." (PMID 25358728, 2014). "However, in another study serum haptoglobin concentrations remained unchanged in dogs with hepatitis or cPSS100." (PMID 35351920, 2022).
liver cancer (7 papers, 2014 to 2024). An epithelial or non-epithelial malignant neoplasm that arises from the liver. "We also identified a proliferative cluster, which mainly consisted of proliferating T cells and a large cluster of HCC cancer cells (40%) expressing both genes associated with normal liver function (ALB, HP, FGA, FGB) and liver cancer (AFP, SPINK1, GPC3, AKR1C1)." (PMID 38030622, 2023). "In the iCCA vs. CIR comparison, seven proteins showed higher abundance in the iCCA patient group, among which haptoglobin (HP), cAMP-dependent protein kinase catalytic subunit beta (PRKACB), heat shock protein (HSP) 90-alpha A2 (HSP90AA2P) were previously reported with respect to liver cancer." (PMID 39286634, 2024).
liver steatosis (7 papers, 2011 to 2025). "The diagnostic or predictive power of haptoglobin in cases of uterine and metabolic diseases, such as hepatic lipidosis, should be investigated in the future in goats." (PMID 40492724, 2025). "Our results show that in comparison to healthy controls, haptoglobin is hyperglycosylated in liver steatosis patients, suggesting hyperglycosylation as a diagnostic marker for early stage NAFLD." (PMID 27725718, 2016). "An example would be staging histology using ALT, ALT, anti-inflammatory markers such as IL-23 to predict inflammation, hepatic steatosis index (HSI) to predict steatosis, and serum fucosylated haptoglobin, a novel diagnostic biomarker, to predict ballooning." (PMID 36613602, 2022). "Liver enzyme activity (ALT, AST, GGT), total bilirubin, lipids fractions, apolipoprotein A1 (ApoA1), α-2-macroglobulin (α2M), haptoglobin (Hp), fasting blood glucose, and fasting insulin are used to generate liver steatosis scores." (PMID 35268466, 2022). "Our third finding that in NAFLD haptoglobin is hyperglycosylated opens new opportunities in biomarker research for fatty liver diseases." (PMID 27725718, 2016). "Here we determined a clear hyperglycosylation of the haptoglobin peptide in sera obtained from liver steatosis patients." (PMID 27725718, 2016). "The normal plasma bilirubin and AST levels and the absence of hepatic steatosis in the MAD20 rats were also associated with significantly increased plasma haptoglobin levels." (PMID 40076444, 2025). "Evidence has demonstrated that the level of haptoglobin was increased in obese mice, and since both leptin and haptoglobin were increased in the NC, this might presumably indicate overweight animals in this group, which also corresponds to the liver steatosis." (PMID 22007198, 2011).
steatosis (7 papers, 2005 to 2025). Increased lipid within the cytoplasm of cells. "An increased glycosylation within the steatosis samples was pronounced when analyzing the haptoglobin glycopeptide." (PMID 27725718, 2016). "An increase in site occupancy was observed in the steatosis samples, whereas the site occupancy of the haptoglobin peptide in the NASH samples is heterogeneous, varying from mildly hypo- to hyperglycosylation." (PMID 27725718, 2016). "The advantage of combining biomarkers of steatosis and those more specific for fibrosis such as A2M, haptoglobin and bilirubin is to adjust the predictive values according to the associated stage of fibrosis." (PMID 16375767, 2005). "Haptoglobin was associated positively with age only in non-obese men and surprisingly positively associated with the grade of steatosis both in obese and non-obese men." (PMID 35327501, 2022).
asthma (6 papers, 2011 to 2025). "Haptoglobin expression correlated negatively with asthma/rhinoconjunctivitis (β = −0.39, p = 0.05), and low 25(OH)D levels (<30 ng/mL) were associated with claudin-1 (β = −2.04, p = 0.0077) and occludin-1 (β = 0.43, p = 0.002)." (PMID 39796069, 2024). "Haptoglobin, secretoglobin and surfactant-D protein have already been identified in the blood of severe and moderate asthma, but their relevance to distinguish between the two forms has not been investigated." (PMID 35911691, 2022). "A systemic involvement has been shown for severe equine asthma by increased acute phase proteins like serum amyloid A and haptoglobin in peripheral blood during exacerbation." (PMID 28053371, 2016). "A plasma protein signature of α2-macroglobulin, haptoglobin, and hemopexin was shown to discriminate between asthma and COPD with 84% accuracy." (PMID 26568662, 2015).
autoimmune disease (6 papers, 2010 to 2025). A disorder resulting from loss of function or tissue destruction of an organ or multiple organs, arising from humoral or cellular immune responses of the individual to their own tissue constituents. "Haptoglobin is associated with several inflammatory and autoimmune diseases including CD." (PMID 20419103, 2010). "Indeed, a common polymorphism in the Haptoglobin gene has been associated with increased cardiometabolic and autoimmune disease risk, and Haptoglobin genotypes have been shown to modify the relationship between dietary intake of vitamin C, an antioxidant, and circulating levels of ascorbic acid." (PMID 22984625, 2012). "Haptoglobin levels can be increased in any disease in which the concentration of acute-phase reactants is increased, such as autoimmune diseases, infections, and malignancies." (PMID 28203576, 2017). "Furthermore, by fine-tuning immune responses, monoclonal antibodies that modulate haptoglobin function are being investigated as potential treatments for inflammatory and autoimmune diseases." (PMID 40606553, 2025). "CD163, known as the haptoglobin‐hemoglobin receptor, is a 130 kDa membrane protein expressed exclusively on monocytes or macrophages that binds and scavenges oxidized and pro‐inflammatory hemoglobin in autoimmune diseases." (PMID 38651547, 2024).
endometriosis (6 papers, 2020 to 2024). The growth of functional endometrial tissue in anatomic sites outside the uterine body. "Inflammatory mediators, such as tumor necrosis factor-α (TNF-α) and interleukin-1β, can increase human endometrial haptoglobin production in female individuals with endometriosis." (PMID 36765791, 2023). "Compared to normal endometrium, endometriosis samples showed elevated levels of heme-degradation-pathway-associated genes: Hmox1 (encoding HO-1), BLVR-A and BLVR-B, and hemopexin (Hx) as well as haptoglobin (Hp), a hemoglobin scavenger." (PMID 35565370, 2022). "The expression level of haptoglobin decreased in the plasma and serum of women with endometriosis." (PMID 39061077, 2024). "Furthermore, one study evaluated the role of haptoglobin in endometriosis and determined that haptoglobin and IL-6 secreted by endometriosis cells decreased the adherence of peritoneal macrophages to the endometrial lesions and contributed to the pathophysiology of endometriosis." (PMID 33302392, 2020).
glioma (6 papers, 2020 to 2024). A benign or malignant brain and spinal cord tumor that arises from glial cells (astrocytes, oligodendrocytes, ependymal cells). "GSN and HP are proteins present in plasma, but they also play a role in meningiomas and gliomas, where GSN is downregulated." (PMID 37627098, 2023). "The processed haptoglobin is expressed in different glioma cell lines in vitro, but the failure to detect haptoglobin protein in the cytosol or serum indicates its transient expression or the need of certain stimuli for haptoglobin to be translated." (PMID 39200114, 2024). "Finally, in order to identify the cell viability kinetics, glioma cells were exposed to M. chamissois crude extract and its partitions HP and CP at 6, 12, 24, and 48 h." (PMID 36771057, 2023). "Furthermore, C1RL probably plays an immunosuppressive role in the pathogenesis of glioma by triggering the activation of haptoglobin and C1s." (PMID 32993564, 2020). "High DEGs in grade II gliomas included NNMT, MFAP5, APCDD1L-AS1, C7orf57, HP, SERPINA5, and LTF and some highly downregulated DEGs included ABCA4, PDE6A, GRP, RD3, and TMEM72." (PMID 33948562, 2021). "On the one hand, due to the suppression of lymphocyte function by haptoglobin, C1RL may modulate immunosuppression in glioma by releasing active haptoglobin." (PMID 32993564, 2020).
Hyperglycemia (6 papers, 2012 to 2024). An increased concentration of glucose in the blood. "As a result, our study identifies a new mechanism of hyperglycemia-amplified inflammation by affecting hemoglobin-haptoglobin interactions with the innate immune system." (PMID 35163309, 2022). "Other common laboratory findings are leucocytosis due to neutrophilia, hyperglycemia, hyperlipemia, and increased troponin, haptoglobin, packed cell volume (PCV), urea, creatinine, and liver enzyme activities." (PMID 23762581, 2012). "A statistically significant increase in TNFα secretion, the ‘classical player’ of the acute-phase immune response, could only be detected 6 h after the stimulation with Hb-Hp complexes in hyperglycemia, regardless of the present haptoglobin variant." (PMID 35163309, 2022). "In our study, we addressed the hypothesis that hyperglycemia can convert the silent clearance function of monocytes to an inflammatory response and examined this hypothesis by analysis of the clearance of hemoglobin-haptoglobin complexes." (PMID 35163309, 2022). "In this study, we show for the first time that hyperglycemia interferes with the tolerogenic hemoglobin-haptoglobin scavenging process via CD163 by human primary macrophages, and elevates the production of inflammatory cytokines in response to hemoglobin-haptoglobin complex uptake." (PMID 35163309, 2022).
non-small cell lung carcinoma (6 papers, 2009 to 2023). A group of at least three distinct histological types of lung cancer, including non-small cell squamous cell carcinoma, adenocarcinoma, and large cell carcinoma. "Haptoglobin has been demonstrated to be produced in comparable levels to the liver in several cancer models, such as non-small cell lung cancer (NSCLC), colorectal cancer (CRC), endothelial adenocarcinoma and ovarian cancer." (PMID 35328392, 2022).
pyometra (6 papers, 2009 to 2025). "Studies have demonstrated elevated haptoglobin levels in cats with pyometra and in other disease models." (PMID 39457917, 2024). "In pyometra cases, C-reactive protein, serum amyloid A and haptoglobin concentrations can be used to monitor early post-OHE complications and ongoing inflammation." (PMID 27829462, 2016). "Acute phase proteins such as c-reactive protein, serum amyloid A and haptoglobin have been shown to increase in pyometra and are mainly found in the α2- and β-globulin fractions." (PMID 19134167, 2009). "In addition, the concentration of APPs, including the C-reactive protein (CRP), serum amyloid A (SAA), and haptoglobin (Hp), were also elevated in dogs with pyometra." (PMID 33732740, 2021). "SPARCLTM assays have been used to quantify haptoglobin, C-reactive protein, AGP and Ceruloplasmin in the plasma of healthy dogs and dogs with pyometra." (PMID 38793672, 2024). "Thus, reversal of the inflammatory process by medical treatment for pyometra does not occur abruptly enough to be detected by fluctuations in haptoglobin and SAA concentrations." (PMID 41463815, 2025).
renal cell carcinoma (6 papers, 2012 to 2025). "Haptoglobin is produced by malignant ovarian epithelium, renal cell carcinoma, and HCC cells." (PMID 31979338, 2020).
renal failure (6 papers, 2019 to 2025). "Elevated levels of haptoglobin in IgAV patients with renal involvement could also be due to subsequent renal insufficiency, as it is linked to a pro-inflammatory response and is more pronounced in advanced stages of chronic kidney disease." (PMID 39953336, 2025). "Identifications of spots of interest by tandem mass spectrometry revealed that many were either known biomarkers for inflammation (complement components), or had previously been suggested as biomarkers for kidney failure (haptoglobin) or liver failure (ceruloplasmin)." (PMID 31568522, 2019).
Cerebral ischemia (5 papers, 2012 to 2023). Restriction of arterial blood supply to the brain associated with insufficient oxygenation to support the metabolic requirements of the tissue. "The Western blot images indicated that the protein expression of haptoglobin and neuromodulin was markedly up‐regulated after cerebral ischemia‐reperfusion." (PMID 34018701, 2021). "Potential therapeutic options to prevent delayed cerebral ischemia ought to concentrate on augmenting the capacity of the intrathecal CD163-haptoglobin–hemoglobin scavenging system and strategies to encourage hemoglobin efflux from the brain." (PMID 22380637, 2012). "With the docking design to galangin, the six proteins (GLUD1, GLUL, GLS, CTH, GOT2 and HP) with high affinity might become its targets for cerebral ischemia." (PMID 27058522, 2016).